VDR (vitamin D receptor)
Diseases named in the same sentence as VDR in open-access papers (continued):
Sharing a sentence is not in itself a finding about the gene and the disease.
alopecia (continued). "Perturbation of VDR expression in humans and mice is associated with alopecia." (PMID 27898044, 2016). "Further therapies that target the enhancement of interaction between guanidinium group of R343 and carboxyl group of E269 by either genetic therapy with correction of this point mutation of VDR might prove to be a curative treatment for alopecia in this family with R343H mutation of VDR34–36." (PMID 29127362, 2017). "The future of alopecia treatment is being shaped by innovative approaches targeting VDR signaling and improved delivery systems." (PMID 41473843, 2026). "This progress, coupled with advances in diagnostic technologies and therapeutic delivery systems, positions VDR‐targeted approaches as a cornerstone in the future management of alopecia and related conditions." (PMID 41473843, 2026). "Different types of alopecia demonstrate distinct relationships with VDR function and vitamin D status." (PMID 41473843, 2026). "VDR variants and dysregulation are widely observed in HVDRR, leading to alopecia and variable clinical responses." (PMID 41473843, 2026). "VDR interaction with its heterodimeric partner RXR is probably pivotal to hair cycling, as the conditional inactivation of RXRα in mouse skin results in alopecia resembling that in VDR-null mice." (PMID 38676447, 2024). "Alopecia is a well-known clinical sign of hereditary vitamin D resistant rickets (HVDRR), a rare disease caused by mutations in VDR." (PMID 39416654, 2024). "About half of VDDR2A, but less so with VDDR2B patients develop alopecia, failure to grow eyelashes and eyebrows due to disrupted VDR, as a functional VDR is required for normal hair follicle cycling." (PMID 34910242, 2022). "Vitamin D-resistant rickets due to inactivating vitamin D receptor mutations is exquisitely rare and more easily distinguished from XLH due to elevated 1,25(OH)2D levels and because almost all patients display alopecia." (PMID 33815294, 2021). "Homozygous knockout of murine vitamin D receptor results in the development of alopecia and near-total HL at 8 months." (PMID 31947635, 2020). "Alopecia due to the defective VDR gene activity within keratinocytes appears in approximately two-thirds of the cases and is considered as a marker of disease severity and response to therapy." (PMID 27796266, 2017). "We identified a novel homozygous R343H mutation in the RXR-binding domain of VDR in a family with HVDRR and refractory alopecia." (PMID 29127362, 2017). "This study was to determine the VDR mutation and the mechanisms of this mutation-causing phenotype in a family with HVDRR and alopecia." (PMID 29127362, 2017). "The impaired VDR function of S360P identified in this study is consistent with the patient’s clinical presentation as severe HVDRR with alopecia." (PMID 28698609, 2017). "We identified a novel homozygous mutation R343H on the VDR gene in a family with typical HVDRR and alopecia." (PMID 29127362, 2017). "VDR KO mice are viable, with moderate developmental defects, such as alopecia and mild colonic inflammation when maintained on calcium rich diet." (PMID 27895587, 2016). "Alopecia due to the defective VDR activity within keratinocytes, appears in approximately two-thirds of cases and is considered a marker of disease severity." (PMID 26422470, 2015). "Natural mutations in the VDR gene in humans result in familial 1,25-dihydroxyvitamin D-resistant rickets (HVDRR), which can be associated with alopecia." (PMID 18213391, 2008). "The stark phenotypic difference between VDR‐null mice (which develop alopecia) and CYP27B1‐null mice (which maintain normal hair despite lacking active vitamin D) underscores that many critical VDR actions in hair follicles operate independently of ligand binding." (PMID 41473843, 2026).
alopecia (continued). "This distinction is critically illustrated by comparing VDR‐null mice, which develop complete alopecia after the first hair cycle, with CYP27B1‐null mice, which lack the enzyme to produce active vitamin D but maintain functional VDR and exhibit normal hair cycling." (PMID 41473843, 2026). "Humans with corresponding VDR-R274L or VDR-H305Q mutations exhibit type II rickets without alopecia." (PMID 39796272, 2025). "Mutations in the DNA-binding domain or RXR interaction site of VDR cause alopecia, whereas mutations in the ligand-binding domain do not." (PMID 39796272, 2025). "Notably, VDR knockout mice aged 8 months exhibited significantly smaller adipocyte sizes compared to their wild-type counterparts, alongside symptoms such as alopecia and heightened energy expenditure." (PMID 39684239, 2024). "Additionally, VDR modulates the immune response in alopecia by interacting with key immune cells, such as T and B lymphocytes, macrophages, and dendritic cells, which are involved in the pathogenesis of autoimmune disorders." (PMID 39416654, 2024). "In addition, affected children are born with normal distribution of hair, and alopecia develops later due to failure of normal hair follicle cycling, which is dependent upon unliganded actions of the VDR." (PMID 32596195, 2020). "This particular type of alopecia is not observed in vitamin D–deficient mice or in Cyp27b1-null mice, suggesting that the action of the VDR in the hair follicle cycle is independent from its ligand." (PMID 30321335, 2019). "Mice and patients who express a truncated VDR that lacks a DNA-binding domain exhibit alopecia, and patients with mutations in RXR but not in the Vit D3 ligand–binding domain also have alopecia." (PMID 29127362, 2017). "In this study, we described a HVDRR patient without alopecia and identified two novel mutations in the VDR gene, one that alters the VDR mRNA translation initiation site and one that affects vitamin D binding activity." (PMID 26422470, 2015). "VDR−/− mice also have alopecia and exhibit keratinocyte stem cell defects." (PMID 23049920, 2012). "Our data may indicate that some of the effects of VDR on the course of L. major infection are ligand independent, as has been shown in the case of alopecia, or that sufficient 1,25D3 persists in mice maintained on the deficient diet to activate the receptor." (PMID 22007288, 2012). "VDR null mice develop rickets and fail to undergo the first postnatal hair growth phase (anagen), resulting in alopecia and conversion of follicles into cysts with IFE differentiation, which is highly reminiscent of the effects of impaired epidermal Wnt signalling." (PMID 18213391, 2008). "Future epigenetic profiling studies, particularly utilizing techniques such as ATAC‐seq and CUT&RUN in hair follicle stem cells, could elucidate how chromatin accessibility at VDR target loci is dynamically regulated during hair cycling and how these patterns differ in various forms of alopecia." (PMID 41473843, 2026). "Recently, we demonstrated that the alopecia observed in vitamin D receptor gene-deficient (Vdr-KO) rats is not seen in rats with a mutant VDR(R270L/H301Q), which lacks ligand-binding ability, suggesting that the ligand-independent action of VDR plays a crucial role in maintaining the hair cycle." (PMID 39796272, 2025). "Moreover, the functions of the VDR and active form of vitamin D do not fully overlap, as evidenced by the development of total alopecia in VDR-deficient mice but not in vitamin-D- or CYP27B1-deficient mice." (PMID 36831327, 2023). "In addition, alopecia has not been reported in patients with point mutations inside the VDR ligand pocket, suggesting that a ligand-independent function of VDR regulates hair follicle homeostasis." (PMID 37673445, 2023). "However, VDR knockout mice also show a lean and alopecia-like phenotype." (PMID 36815991, 2023).
alopecia (continued). "Functional analyses revealed various features of several mutations of VDR in patients with or without alopecia, and showed that a single amino acid substitution could cause wide disruption of the protein function." (PMID 28698609, 2017). "Vitamin D receptor (VDR) signaling plays a crucial role in hair follicle biology and represents a promising therapeutic target for various forms of alopecia." (PMID 41473843, 2026). "In addition, previous data indicate that VDR mutations cause defects in DNA binding, and that RXR heterodimerization or the absence of VDR causes alopecia, and mutations that alter VDR affinity for 1,25(OH)2D3 or disrupt coactivator interactions do not cause alopecia." (PMID 28377956, 2015). "Consequently, there is a pressing need to decipher how VDR dysfunction influences the local immune microenvironment and its subsequent impact on follicle cycling, as this knowledge could reveal novel therapeutic targets and approaches for treating various forms of alopecia." (PMID 41473843, 2026). "Although these rats showed abnormal bone formation, no alopecia was observed, suggesting that unliganded VDR plays an important role in hair cycle maintenance." (PMID 37898650, 2023). "It has been demonstrated that VDR KO mice showed premature aging features, such as alopecia, thickened skin and epidermal cysts, although no changes in the number of Purkinje cells in the cerebellum were found." (PMID 36831327, 2023). "Without affecting the expression, conformation, nuclear location of VDR or heteridimerization with RXR, VDR-R343H impairs the transactivation activity of VDR on downstream transcription, accounting for HVDRR features with alopecia." (PMID 29127362, 2017). "Expression of a VDR-L417S mutant in VDR null mouse skin delays, but does not completely rescue, alopecia." (PMID 18213391, 2008). "In vivo, expression of a mutant VDR that can bind β-catenin but not vitamin D (L233S) rescues alopecia in VDR null mice, demonstrating ligand independent functions of the VDR in skin." (PMID 18213391, 2008). "Alopecia is associated with VDR mutations that impair DNA binding, RXR heterodimerization, or production of the VDR, while mutations that alter VDR affinity for 1,25(OH)2D or disrupt coactivator interactions do not cause alopecia." (PMID 32596195, 2020). "The alopecia observed in the VDR−/− mice is independent of 1,25(OH)2D3 expression." (PMID 23049920, 2012). "Furthermore, the lack of alopecia in our patient indicated that H229Q VDR do not interfere with the heterodimerization with RXR, since patients with mutations affecting the VDR-RXR heterodimerization (residues F251, Q259, V346, and R391) all presented with alopecia." (PMID 26422470, 2015). "However, alopecia is considered as VDR-mediated but not calcium-mediated phenotype, and was unresponsive to high calcium diet, which was also similar to the observations on VDR-null mice." (PMID 26153892, 2015).
periodontitis (42 papers, 2010 to 2026). An acute or chronic inflammatory process that affects the tissues that surround and support the teeth. "Specific VDR genotypes have been correlated with periodontitis, resulting in increased ABL, CAL, and tooth loss." (PMID 40422620, 2025). "Certain genetic polymorphisms have been studied for their association with chronic periodontitis including several interleukin genes, the vitamin D receptor, the FcγRIIIb-NA1 gene, the tumor necrosis factor-β gene, and several human leukocyte antigen variants." (PMID 37570272, 2023). "It is also suggested that genetic variants of the vitamin D receptor are a biomarker for periodontitis." (PMID 35215516, 2022). "Several authors have considered the potential impact of FokI, BsmI, ApaI, and TaqI VDR gene variants as potential genetic factors involved in susceptibility to periodontitis." (PMID 35740958, 2022). "Genetic polymorphisms of matrix metalloproteinase-3 (MMP-3) and vitamin D receptor (VDR) predispose an adolescent to periodontitis." (PMID 35757444, 2022). "Notwithstanding, the VDR variants’ impact on periodontitis still remains to be consolidated since it depends on the number of studies, and is expected to increase considerably in the future." (PMID 32438644, 2020). "In two recent evidence-based studies, a number of VDR polymorphisms were correlated with higher risk of developing periodontitis." (PMID 32438644, 2020). "From a genetic perspective, the role of VDR variants in periodontitis has been the subject of great consideration." (PMID 32438644, 2020). "The connection between the VDR ApaI polymorphism and periodontitis cause has been attached the attention by many researchers." (PMID 31763010, 2019). "As a result, we proceeded this analysis to more accurately estimate the relationship between VDR‐ApaI polymorphism and periodontitis susceptibility among Chinese population." (PMID 31763010, 2019). "Totally 62 studies that examined the relationship between the VDR polymorphisms and the risk of periodontitis were distinguished after document duplication was deleted in different databases." (PMID 31763010, 2019). "To better address the relationship between VDR ApaI polymorphism and periodontitis risk, we conducted a meta‐analysis of Chinese population to reduce the impact of different genetic backgrounds." (PMID 31763010, 2019). "Lots of studies are conducted to explore the correlation between VDR ApaI variants and periodontitis previously." (PMID 31763010, 2019). "A cumulative analysis further implied a shortage of correlation between the VDR ApaI polymorphism and the risk of periodontitis among the Chinese population." (PMID 31763010, 2019). "One cross-sectional study suggested the interaction between smoking and vitamin D receptor gene polymorphism (CC+CT genotypes of FokI) increased the risk of periodontitis (OR = 9.6, 95%CI: 4.5- 20.4)." (PMID 30112011, 2018). "Recently, it was reported the relationship between FokI polymorphism of VDR and susceptibility to chronic periodontitis, AIDS disease or more active immune system for the shorter FokI-VDR variant." (PMID 28427151, 2017). "Genetic polymorphisms of pro‐inflammatory mediators MMP3, CD28, and VDR seem to link to initial periodontitis." (PMID 29744169, 2016). "Vitamin D receptor Taq-I TT polymorphism was moderately associated with both the presence and progression of periodontitis in smokers." (PMID 20170537, 2010). "The relationship between VDR gene variants and periodontitis has garnered considerable attention." (PMID 40422620, 2025). "Recent meta-analyses have indicated that the FokI gene polymorphism for VDR is significantly associated with heightened susceptibility to periodontitis, while associating BsmI polymorphism with FokI has been linked to an increased risk of developing periodontitis in the general population." (PMID 40422620, 2025).
periodontitis (continued). "Furthermore, single-nucleotide polymorphisms (SNPs) in genes such as VDR (Vitamin D Receptor) have been associated with increased susceptibility to both periodontitis and AD, highlighting a potential genetic link between oral health and neurodegeneration." (PMID 41471945, 2025). "Furthermore, the vitamin D receptor (VDR) gene plays a role in immune response and bone metabolism, with polymorphisms in the VDR gene linked to an increased risk of periodontitis, suggesting a role of vitamin D metabolism in periodontal health." (PMID 39189252, 2024). "Studies have explored histocompatibility antigen polymorphisms, IgG class antibody receptor polymorphisms, CD14 molecule polymorphisms, toll-like receptor polymorphisms, vitamin D receptor polymorphisms, and other cellular receptor polymorphisms in relation to chronic and aggressive periodontitis." (PMID 37927745, 2023). "We analyzed the genetic variants on the VDR gene in a cohort of 50 Italian periodontal patients and 41 healthy control subjects in order to investigate both a potential correlation with the disease susceptibility and the presence and quantity of periodontopathogenic bacteria." (PMID 35740958, 2022). "Thus, far, several studies have analyzed the influence of the VDR polymorphisms rs2228570, rs1544410, rs7975232, and TaqI and their combinations on periodontitis." (PMID 32375337, 2020). "Subgroup analysis by geographic area (s), control source and periodontitis type, significant correlations between the VDR ApaI periodontitis and variants were found in north China (a vs. A, OR = 0.64, CI = 0.47–0.85; aa vs. AA, OR = 0.48, CI = 0.28–0.82; aa vs. AA + Aa, OR = 0.50, CI = 0.31–0.79)." (PMID 31763010, 2019). "All in all, the meta‐analysis suggests that VDR ApaI polymorphism may be connected with a reduced cause of periodontitis in northern China; however, much more researches should be investigated in the future to verify our findings." (PMID 31763010, 2019). "The outcomes showed that VDR‐ApaI polymorphism may be related to the significant reduction of periodontitis risk in North China due to the small sample size." (PMID 31763010, 2019). "The evidence is accordant with our findings, suggesting that the correlation between VDR ApaI variants and periodontitis may be contributed not only to ethnic background, region and sample size, but also to different mechanisms of AP and CP." (PMID 31763010, 2019). "Additionally, vitamin D receptor polymorphisms and for vitamin D binding protein appear to have some impact on increasing the risk for periodontitis." (PMID 30558282, 2018). "In addition, it has been shown that VDR polymorphism, in the presence of exogenous aetiological factors (i.e., tobacco smoke and alcohol), is associated with increased risk of chronic periodontitis and other inflammatory conditions." (PMID 30364037, 2018). "Previous clinical studies link VDR polymorphism to the chronic and aggressive periodontitis." (PMID 24587317, 2014). "These authors presented that single nucleotide polymorphisms in the IL-1α, IL-1β, IL1RN, IL-6, IL-10, TNF-α, transforming growth factor β1 (TGF-β1), interferon γ (IFN-γ) and vitamin D receptor (VDR) may be associated with susceptibility to chronic periodontitis." (PMID 35453197, 2022). "In turn, the 1,25(OH)2D/VDR signalling induces the expression of genes encoding the antibacterial agents cathelicidin and β defencin which may provide some protection against the development of bacterial plaque-induced chronic periodontitis." (PMID 30364037, 2018). "Associations between vitamin D receptor (VDR) polymorphisms (FokI, BsmI, TaqI, ApaI) and periodontitis have been extensively studied, but results are heterogeneous." (PMID 41300760, 2025). "Several polymorphisms were associated with periodontitis, including the Fc-γ receptor, ILs-1,4,6,10,18, TNF-α, vitamin D receptor, cluster of differentiation-14, MMP-1, Toll-like receptor-2 and 4, and COX-2." (PMID 33340075, 2021).